CD44 (CD44 molecule (IN blood group))
Diseases named in the same sentence as CD44 in open-access papers (continued):
Sharing a sentence is not in itself a finding about the gene and the disease.
tumor (continued). "Potential therapeutic strategies targeting CD44-positive tumors via effectively blocking CD44, destroying HA-CD44 balance and increasing cellular concentration of anti-tumor drugs generate hope for anti-tumor drug development." (PMID 33303029, 2020). "The CS-GAG moiety serves as the structural motif for SRGN binding to tumor cell surface CD44 and promotes cell migration." (PMID 31898491, 2020). "Both ISH and RNA-Seq data demonstrated that diverse regions of the tumor can be delineated based on CD44 and CA9 expression whose pattern was correlated." (PMID 32823815, 2020). "Then β-catenin enters into the nucleus of tumor cells and upregulates the downstream markers such as CD44, TCF1/TCF7, and C-Jun to drive tumor carcinogenesis or EMT related genes such as N-cadherin, Vimentin, and Slug to mediate EMT process." (PMID 33505307, 2020). "CD44 expression in ER+ (n = 129) or ER− (n = 112) tumor samples was assessed by immunohistochemical analysis." (PMID 33024087, 2020). "CD44 is a marker of tumor stem cells and has prognostic value in various tumors, but its role in LGG is unclear." (PMID 33381460, 2020). "A fluorescent anti-CD44 antibody was used to challenge the encapsulated co-culture of tumor cells and fibroblasts." (PMID 33203360, 2020). "These lead compounds proved suitable in cellulo and in vivo to impair oncoRBP function, as demonstrated here by the inhibition of MSI1-enhanced CD44 expression and induction of tumor cell differentiation by the MSI1 inhibitor luteolin." (PMID 33291443, 2020). "Newly synthesized high molecular weight hyaluronic acid (HMW-HA) is bound by CD44, while at a later disseminating stage of tumor progression, HMW-HA is fragmented by hyaluronidases and the resulting low molecular weight (LMW)-HA fragments." (PMID 33379400, 2020). "Further studies will be needed to unravel the mechanisms by which MMP9 drives CD44 mediated invasion and tumour progression." (PMID 32445177, 2020). "EVs expressing CD44 have been shown to promote tumor cell aggressiveness and metastasis mainly by contributing to the pre-metastatic niche." (PMID 33050539, 2020). "In another study, CD44 antibody-mediated liposomal nanoparticles in HCC promoted apoptosis and reduced tumor growth through specifically targeting CD44." (PMID 32466488, 2020). "The results show that among the 6 CSC markers investigated, the expression of CD44 and its variant isoforms (CD44v6 and CD44v8-10), and also ALDH1A1, were associated with tumor progression and poor outcome of CCA patients, including short RFS and OS." (PMID 32039729, 2020). "Previous studies have shown that BRG1 is required to enable the expression of CD44 in tumor cells as well as to provide a mechanism for the activation of CD44 expression depending on the chromatin remodeling activity mediated by BRG1." (PMID 33071648, 2020). "Recently, in vitro results suggested that PKM2 interacts with CD44, a cell surface marker for cancer stem cells and enhances the glycolytic phenotype of tumor cells." (PMID 32326107, 2020). "CD44 is another tumor cell receptor for ECM proteins, more specifically, a highly polymorphic receptor for hyaluronan (HA), part of the immunoglobulin receptor superfamily, and a surface proteoglycan." (PMID 32943996, 2020). "In particular, HA-induced CD44 conformational changes and subsequent cytoskeletal modifications promote tumor cell migration, invasion, and epithelial-to-mesenchymal transition (EMT)." (PMID 32793493, 2020). "Their low levels in orthotopic tumors indicated that transplanted CXCR4+MET+CD44+ cells differentiated and lost marker expression during tumor formation." (PMID 32066735, 2020).
tumor (continued). "These cells were detected simultaneously in the primary tumor and peripheral blood in 18.18% of cases compared with CD44+CD24-N-cadherin- CTCs." (PMID 32316333, 2020). "We established the delivery vehicle using tumor-derived exosomes loaded with siRNA against CD44 to disrupt the CD44 expression of MCF-7/ADR cells." (PMID 32760666, 2020). "Aurora‐A kinase reportedly induces chemoresistance by upregulating CD44 and maintaining tumor stemness in cancer cells." (PMID 32725633, 2020). "Combination group showed significantly smaller tumor volume than CD44-targeted NIR-PIT group at 12 and 17 days after NIR-PIT (p < 0.05, Tukey–Kramer test)." (PMID 32937841, 2020). "Apart from the promoting effects CD44 exerts on cancer progression, aberrant expression of CD44 can also contribute to therapy resistance during anti-tumor management." (PMID 33303029, 2020). "Since both podoplanin and CD44 have been described as components of tumor invasion-related invadopodia, we are currently investigating the role of podoplanin interaction with CD44s and CD44v in invadopodia formation and activity." (PMID 33003440, 2020). "Inflammatory cytokine arrays were used as a screening tool to detect changes within tumor cell conditioned media collected from CD44 WT and KO Hs578T and MDA-MB-231 cells." (PMID 32455980, 2020). "CD44 participates in a diversity of signaling and pathways involved in both physiological and pathological processes, especially in carcinogenesis and tumor progression." (PMID 33303029, 2020). "Accumulating evidence has shown that BCSCs with ALDH1+ and the CD44+/CD24−/low phenotype are responsible for tumor initiation, progression, metastasis, and drug resistance." (PMID 33327542, 2020). "Our HA-capped AuNPs exhibited an enhanced inhibitory activity against Escherichia coli ATCC 9637 and Staphylococcus aureus ATCC 29213 as well as a better targeted cytotoxicity towards CD44-positive tumor cells than the bare, glucose-capped, AuNPs." (PMID 32349323, 2020). "Another significant engagement of CD44 in enhancing tumor activities and progression is through the HA-mediated CD44 pathway by triggering intracellular miRNA and Rho GTPase signaling." (PMID 32429463, 2020). "Our results suggest that tumor cells responding to HA through CD44 help maintain a chronic inflammatory state by regulating cytokine synthesis." (PMID 32455980, 2020). "In pleomorphic adenoma, knockdown of CD44 not only impaired the malignant behaviors of tumor-initiating cells in vitro, but also suppressed tumorigenesis in xenograft mice." (PMID 33303029, 2020). "As one of the adhesion molecules related to tumor metastasis, CD44, a receptor of hyaluronan (HA), is becoming attractive for its role as a stem cell marker." (PMID 33292278, 2020). "CD44 is a widely expressed cell surface adhesion molecule that is overexpressed in several neoplasms and involved in cancer cell proliferation, differentiation, migration, angiogenesis, and disease progression." (PMID 31963556, 2020). "CD44 expression was lower in MOC1 tumor tissues than MC38-luc and LL/2 tumors, which has also been demonstrated by flow cytometry analysis in the previous study." (PMID 32937841, 2020). "The combination of IL-15 administration and CD44-targeted NIR-PIT showed superiority in survival to IL-15 treatment alone in all three tumor types tested here." (PMID 32927646, 2020). "Among tumor antigens, beyond CD44 and CD133, CD20 is considered a good target too, especially for melanoma-initiating cells." (PMID 32731612, 2020). "BCSCs have been isolated from tumor samples and breast cancer cell lines using a combination of surface markers such as CD44, CD24, EpCAM, CD133 and ALDH, among others." (PMID 32183150, 2020).
tumor (continued). "NIR-PIT using anti-CD44-mAb-IR700 induces effective tumor killing in CD44-expressing syngeneic mouse models." (PMID 32927646, 2020). "CD44 expressed on tumor cells binds to platelet P-selectin and interacts with fibrin to establish firm adhesion between platelets and tumor cells." (PMID 32943996, 2020). "CD44 is a well-known marker that plays an important role in tumor progression, but the different isoforms work differently." (PMID 32039729, 2020). "In parallel, in accordance to previous reports that CD44 regulates Rho-family of GTPases to promote tumor progression, we show that SRGN promoted cytoskeleton reorganization via inducing Rac1 and CDC42 activation." (PMID 31898491, 2020). "The surface glykoprotein CD44 is frequently expressed by tumor cells and mediates tumor cell migration by binding collagen as a constituent of the ECM." (PMID 32092981, 2020). "Analyses of the PBI-05204–treated U87 cells revealed significant 73% declines in expression of Sox2 and a moderate reduction of other tumor stem cell markers CD44 and CXCR4." (PMID 33013390, 2020). "Taken together, numerous studies demonstrate the beneficial effects of CD44 inhibition on tumor progression." (PMID 33335857, 2020). "Surprisingly, negative correlations between the percentage of tumour-infiltrating NK cells, CD8+ T lymphocytes or activated CD8+ CD44+ T lymphocytes and tumour weight were detected only in histamine-treated H4R knockout (KO) mice." (PMID 31748740, 2020). "The tumor growth was arrested and both the CD44+/CD24−/low and ALDH+ BCSC populations were decreased in the xenograft model with the inhibition of γ-secretase, which prevents the formation of the active Notch intracellular domain (NCID)." (PMID 33327542, 2020). "Knockdown of IL-17RB, MUC1 and/or MUC4 also suppresses expression of stemness-related markers, such as SOX2, Nanog, Oct-4, and CD44, and inhibited tumor sphere formation." (PMID 33082357, 2020). "Second, the pooled analyses of the relationships between CD44 expression and the prognosis and patient clinicopathological features such as tumor grade and T stage." (PMID 32434417, 2020). "CD44-targeted NIR-PIT combined with CTLA4 blockade showed greater tumor growth inhibition with longer survival compared with CTLA4 blockade alone in all tumor models." (PMID 32937841, 2020). "The combination group showed significantly greater tumor reduction compared with IL-15 treatment or CD44-targeted NIR-PIT groups at 5, 7, and 10 days (p < 0.05, Tukey–Kramer test)." (PMID 32927646, 2020). "Hyaluronan receptors, such as Cluster of differentiation 44 (CD44), are highly expressed on stem cells in normal tissues and tumor-initiating cells isolated from neoplastic tissues." (PMID 32231069, 2020). "In cSCC cell lines, miR-199a targeted CD44 to repress the proliferation, migration and invasion of tumor cells, and regulated the interaction between CD44 and Ezrin, a complex involved in metastasis." (PMID 32674318, 2020). "Here, we show that tumor progression blocks the transition of Lin−Thy1.2+CD25+CD44+c-KitlowDN2b to Lin−Thy1.2+CD25+CD44−c-Kit−DN3 in T-cell maturation, instead leading to DN2-T-cell differentiation into dendritic cells (DC)." (PMID 32582141, 2020). "Significant heterogeneity was found between CD44 expression and tumor grade (P < 0.001) and T stage (P = 0.001)." (PMID 32434417, 2020). "CD44 is a cancer stem cell marker that participates in a diverse set of functions in tumor cells, inculding cell proliferation, cell-to-cell adhesion, migration, invasion, and blood vessel development." (PMID 31511651, 2020). "CD44 shedding and the delocalization of focal adhesion complexes from rafts induced by cholesterol depletion inhibited tumor cell migration." (PMID 32862200, 2020).
tumor (continued). "The numbers of memory T cells in LN increased more significantly compared with those in the subcutaneous tumor, while the effector CD8+ T cells (CD8+ CD44− CD62L−) in the tumor increased more significantly in the tumor compared with those in the LN region." (PMID 32508058, 2020). "CD44 is a well-known marker of cancer stem cells and anti-CD44-mAb-IR700 NIR-PIT induces effective tumor killing in CD44-expressing syngeneic mouse models." (PMID 32937841, 2020). "This interaction was instrumental in promoting a spheroid formation, as well as cell growth/self-renewal properties in CD44+ tumor cells." (PMID 32793478, 2020). "In this study, since multiplex immunohistochemistry was technically difficult immediately after CD44-targeted NIR-PIT due to severe damage on tumor tissue that lead to ill-defined tumor boarder, we performed ex vivo CD44-targeted NIR-PIT on behalf." (PMID 32937841, 2020). "The counts of CD44+CD24− BCSCs and CD44+CD24−CD44+ BCSCs were also significantly decreased in the tumor tissues of mice treated with the miR-7 agomir and in the Ad plus Cy group." (PMID 32143670, 2020). "Extensive evidence has suggests that CD44 plays crucial roles in tumor aggressiveness and metastasis, especially with CSCs related characteristics." (PMID 32434417, 2020). "Apart from their crucial role in tumor angiogenesis, the TECs are capable of enriching the CD44+/CD24neg/low BCSCs." (PMID 32883003, 2020). "Fibronectin is also a ligand for CD44, which is thought to also play a key role in the evasion of apoptosis for tumour-derived cells in the early stages of colonisation." (PMID 32679759, 2020). "When the therapeutic agent arrived at the tumor tissues, the combination of HA and CD44 promoted endocytosis and TPP triggered mitochondrial aggregation after lysosome escape." (PMID 34123080, 2020). "Activated CD44 proteins interact with several intracellular signaling networks that support the oncogenic properties of tumor cells and drive cancer progression, metastasis, and therapy resistance across various cancer models." (PMID 33335857, 2020). "In an in vivo xenograft model, the ALDH+CD44+ subset displayed tumour-initiating and self-renewal characteristics." (PMID 32390009, 2020). "This clearly indicates that CD44 has a basic role in tumor invasion and migration, thus supporting several reports that described CD44 as a marker of GSCs." (PMID 32429463, 2020). "Osteopontin can also bind to CD44 and subsequently promotes cell signaling involved in tumor progression and metastasis." (PMID 33303029, 2020). "Data have stated that CD44 is involved in tumor-initiating that includes CD44 self-interaction and downstream signal activation." (PMID 33292278, 2020). "In the in vivo tumorigenesis assay, mice in the ALDH+CD44+ group formed significantly larger tumours, compared to the ALDH−CD44− group." (PMID 32390009, 2020). "CD44 is a transmembrane glycoprotein highly expressed in almost every cancer cell and is crucial in tumor initiation and colonosphere propagation in vitro." (PMID 32821342, 2020). "In this study, we showed that CD44-targeted NIR-PIT suppressed tumor growth and increased activation and tumor infiltration of CD8+ T cells resulting in a complete remission in approximately 15% of MOC2-luc tumor-bearing mice." (PMID 33322807, 2020). "Mice treated with Rapalink-1 showed a significantly delayed tumor growth compared to control and cells recovered from the tumors of treated animals showed a marked decrease of CD44 expression." (PMID 32656088, 2020). "An invasive tumor in fact, to expand, attacks the extracellular matrix of the surrounding tissues and CD44, together with hyaluronic acid, certainly plays a decisive role in the various cellular pathways." (PMID 32349323, 2020). "Apart from CD44 itself as a promising target in cancer treatment, it has also been suggested to probably act as a biomarker for anti-tumor drug targeting to CD44-positive cancer cells." (PMID 33303029, 2020).
tumor (continued). "Remarkably, immunofluorescence analyses revealed a more pronounced localization of CD25+CD44+ DN2 T cells at cortico-medullary junctions of thymus in tumor-bearing vs. tumor-free mice." (PMID 32582141, 2020). "Accordingly, miR-143 was subsequently shown to work as a tumor suppressor, through its interaction with CD44, despite the role of CD44 in the maintenance of cancer stem cells properties." (PMID 32731349, 2020). "We gained insight into the plasticity of CD133/CD44 expression, in particular in the unique LS1034 cell line model, thereby addressing novel aspects underlining the relevance of the stromal tumor microenvironment for engraftment and phenotypic interconversion." (PMID 32685007, 2020). "As shown inFigure 2C, activity of the CD44 along with proteoglycanhyaluronan (HA) in MAPK signaling pathway is associatedwith growth and survival of tumor cells [P=1.5×10-6, falsediscovery rate (FDR) correction=0.0002]." (PMID 31376327, 2020). "Pathophysiologically, CD44 is involved in the processes of cell growth, survival, differentiation, motility, tumor growth, proliferation, and metastasis." (PMID 32232385, 2020). "Taken together, these results further indicate that CD44-expressing TMPs contribute to the inhibition of cell adhesion and cytoskeleton re-arrangement, and thus enhance the metastatic properties of tumor cells." (PMID 33050539, 2020). "CCT administration reduced tumor proliferation, thereby producing less compact tumors with a very low expression of the mesenchymal marker CD44 and an increased expression of the neuronal marker β3-tubulin." (PMID 31936544, 2020). "In association with this, immunohistochemistry (IHC) investigations showed, similar to what was seen in vitro, decreased CD44 and increased β3-tubulin expression in the tumor tissues of treated animals." (PMID 31936544, 2020). "The identification of AKAP8 in suppressing EMT and cancer metastasis was through a biochemical approach to capture proteins that interact with hnRNPM, previously shown to promote EMT and tumor metastasis by regulating alternative splicing of CD44." (PMID 31980632, 2020). "CD44-targeted NIR-PIT also eliminates pre-existing activated immune cells in tumor beds because CD44 is expressed in not only cancer stem cells but also effector immune cells." (PMID 32937841, 2020). "CAMs, such as cadherin, integrins, selectins, immunoglobulins, and CD44, are known to play a key role in each step of the metastasization process and are expressed in NB tumor cells." (PMID 32825087, 2020). "The necrotic fraction of tumor slices (49.5 ± 7.9%) correlated negatively with depth in the tissue (Pearson correlation R = −0.88, p < 0.01), CD44 expression (R = −0.61, p = 0.02) and the DAPI-positive area (R = −0.71, p < 0.01)." (PMID 32560230, 2020). "Similar to in vitro results, the stem cell marker CD44 was also decreased in mouse tumor tissues upon TQ treatment." (PMID 32821342, 2020). "This study aims to investigate the possibility of CD44-targeted NIR-PIT in a poorly immunogenic tumor model, MOC2-luc, to induce additional antitumor immunity and sensitize it to anti-PD-1 ICI when given as a combination therapy." (PMID 33322807, 2020). "CD44-targeted NIR-PIT in combination with other therapies showed promising results in MC38-luc and LL/2 but was less effective against MOC1 tumor which has low CD44 expression and fewer CD44 positive tumor cells compared to MC38-luc and LL/2." (PMID 32927646, 2020). "Pre-treating TMPs with anti-CD44 antibodies restored the invasive properties of TMP-exposed tumor cells to control levels." (PMID 33050539, 2020). "Several markers significantly correlated with CD3 expression in the tumour compartment, including CD40, CD44, CD14, B2M, Tim-3, CD8, CD45RO, and ICOS, potentially implicating other cell lineages in immune-associated anti-tumour activity." (PMID 33261133, 2020).